KRTCAP2 (keratinocyte associated protein 2)
Description:
Subunit of STT3A-containing oligosaccharyl transferase (OST-A) complex that catalyzes the initial transfer of a defined glycan (Glc(3)Man(9)GlcNAc(2) in eukaryotes) from the lipid carrier dolichol-pyrophosphate to an asparagine residue within an Asn-X-Ser/Thr consensus motif in nascent polypeptide chains, the first step in protein N-glycosylation. N-glycosylation occurs cotranslationally and the complex associates with the Sec61 complex at the channel-forming translocon complex that mediates protein translocation across the endoplasmic reticulum (ER). Within the OST-A complex, acts as an adapter that anchors the OST-A complex to the Sec61 complex. May be involved in N-glycosylation of APP (amyloid-beta precursor protein). Can modulate gamma-secretase cleavage of APP by enhancing endoprotelysis of PSEN1.
Synonyms: KCP2
Tractability: Antibody: UniProt predicts a signal peptide or a membrane-spanning region. PROTAC: its protein half-life has been measured.
Gene: Protein-coding gene on chromosome 1 (155,169,408 to 155,173,475, reverse strand). Ensembl gene ENSG00000163463.
Subcellular location: Endoplasmic reticulum; Endoplasmic reticulum membrane
Gene Ontology:
Molecular function: enzyme activator activity; protein-macromolecule adaptor activity
Biological process: protein N-linked glycosylation
Cellular component: endoplasmic reticulum; endoplasmic reticulum membrane; oligosaccharyltransferase complex; oligosaccharyltransferase complex A
Genetic constraint (gnomAD): Loss-of-function variants: 9 observed, 15.1 expected, observed/expected ratio (o/e) 0.6, 90% interval 0.36 to 1.04. The upper end of that interval is the gene's LOEUF score, 1.04, which puts it in group 4 of 6, group 1 being the genes least tolerant of losing a copy. Missense variants: 150 observed, 158.75 expected, observed/expected ratio (o/e) 0.94, 90% interval 0.83 to 1.08. Synonymous variants: 67 observed, 70.09 expected, observed/expected ratio (o/e) 0.96, 90% interval 0.78 to 1.17.
Homologues: Orthologues: macaque KRTCAP2 (100% identical), chimpanzee KRTCAP2 (99% identical), pig KRTCAP2 (99% identical), dog KRTCAP2 (97% identical), mouse Krtcap2 (97% identical), guinea pig KRTCAP2 (96% identical), rat Krtcap2 (96% identical), tropical clawed frog krtcap2 (76% identical), zebrafish krtcap2 (74% identical), Drosophila melanogaster CG31460 (21% identical).
Diseases named in the same sentence as KRTCAP2 in open-access papers:
KRTCAP2 is named in the same sentence as 18 diseases in open-access papers, as found by Europe PMC text mining. Sharing a sentence is not in itself a finding about the gene and the disease. The quoted sentences say what the papers report.
gout (2 papers, 2024). A condition characterized by painful swelling of the joints, which is caused by deposition of urate crystals. "Additionally, KRTCAP2 was identified as a primary gene increasing the risk of gout." (PMID 39161423, 2024). "We identified 17 association signals for gout at unique genetic loci, including four genes related by protein-protein interaction network (PPI) analysis: TRIM46, THBS3, MTX1, and KRTCAP2." (PMID 38831441, 2024). "Elevated expression of KRTCAP2 and PGAP3 is linked to an increased risk of gout, whereas higher expression of THBS3, THBS3-AS1, and KAT5 is associated with a reduced risk of the disease." (PMID 39161423, 2024). "The genes MAP3K11, KRTCAP2, and PCNX3 influence the function of macrophages, plasma cells, and MDCs, respectively, to increase gout risk." (PMID 38831441, 2024). "This study identified 17 genetic loci associated with gout, including four genes related by protein-protein interaction network (PPI) analysis: TRIM46, THBS3, MTX1 and KRTCAP2." (PMID 38831441, 2024). "Notably, increased expression of KRTCAP2 and PGAP3 is associated with an increased risk of gout, whereas increased expression of THBS3, THBS3-AS1, and KAT5 is associated with a reduced gout risk." (PMID 39161423, 2024). "The study also found that genes such as TRIM46, MAP3K11, KRTCAP2, and TM7SF2 could potentially elevate the risk of gout." (PMID 38831441, 2024). "This study also identified 22 methylation sites related to gout, and genes that may increase the risk of gout, such as TRIM46, MAP3K11, KRTCAP2 and TM7SF2." (PMID 38831441, 2024). "Specifically, KRTCAP2, as a keratin-associated protein, may play a key role in maintaining the structure and function of immune cells such as macrophages and neutrophils, while PCNX3 may influence the progression of gout inflammation by regulating cellular responses to inflammatory signals." (PMID 38831441, 2024). "Finally, we found by single-cell analysis that MAP3K11, KRTCAP2, PCNX3, and TM7SF2 demonstrate potential significant roles in the pathogenesis of gout." (PMID 38831441, 2024). "Although the precise roles of KRTCAP2 and PCNX3 in gout are not fully clear, their biological functions suggest they may indirectly participate in the pathological process of gout through affecting cellular skeletal stability, cell signaling, and stress responses." (PMID 38831441, 2024).
Parkinson’s (2 papers, 2023 to 2025). "Dementia-related genes ARHGAP27, CYP1B1, KANSL1, KRTCAP2, LSM7, and GBA are also linked to altered behavior, neurodegeneration, inflammation, and Parkinson’s." (PMID 37588516, 2023).
uveal melanoma (2 papers, 2025). A melanoma derived from melanocytes of the uveal tract. "Elevated expression of KRTCAP2 has also been associated with unfavorable prognosis in uveal melanoma, further underscoring its role as a prognostic marker." (PMID 40315225, 2025). "In the uveal melanoma cohort, a six‐molecule signature (ARPC1B, BTBD6, GUSB, KRTCAP2, RHBDD3, and SLC39A4), which was associated with glycolysis and the immune response, was established and used for survival prediction and risk stratification of these patients." (PMID 39830021, 2025).
allergic disease (1 paper, 2020). An immune response that occurs following re-exposure to an innocuous antigen, and that requires the presence of existing antibodies against that antigen. "The remaining 3 represent novel associations for allergic disease: rs184587444 in SPRR2A, rs4971089 in KRTCAP2, and rs4809619 in EYA2." (PMID 32603359, 2020).
Alzheimer disease (1 paper, 2024). A progressive, neurodegenerative disease characterized by loss of function and death of nerve cells in several areas of the brain leading to loss of cognitive function such as memory and language. "KRTCAP2 has been linked to autoimmune plasmatic dysplasia, Alzheimer’s disease, and numerous tumor types." (PMID 38831441, 2024).
bladder cancer (1 paper, 2022). "Then, 9 target genes that were differentially expressed between bladder cancer and normal samples were screened (FDR < 0.05), in which upregulated expression of RHBG, PAQR6, CLK2, KRTCAP2, FLAD1, HCN3 were correlated with bad survival of patients with bladder cancer." (PMID 36186809, 2022).
gastric cancer (1 paper, 2025). A primary or metastatic malignant neoplasm involving the stomach. "Additionally, KRTCAP2 has been shown to regulate tumor cell proliferation, differentiation, and carcinogenesis in gastric cancer." (PMID 40315225, 2025).
glioma (1 paper, 2026). A benign or malignant brain and spinal cord tumor that arises from glial cells (astrocytes, oligodendrocytes, ependymal cells). "Keratinocyte-associated protein 2 (KRTCAP2) encodes a corresponding protein involved in N-glycosylation, yet its functional and clinical relevance in glioma remains poorly understood." (PMID 41676149, 2026). "Depletion of KRTCAP2 significantly inhibited the proliferative, migratory, and invasive capacities of glioma cells, confirming its role as an oncogenic driver." (PMID 41676149, 2026). "The study highlights its clinical significance and multifaceted role in shaping an immunosuppressive glioma microenvironment, underscoring KRTCAP2 as a promising therapeutic target." (PMID 41676149, 2026).
hepatocellular carcinoma (1 paper, 2025). A malignant tumor that arises from hepatocytes. "Previous research has shown that elevated levels of KRTCAP2 protein are associated with reduced infiltration of CD8+ T cells and CD68+ macrophages in hepatocellular carcinoma tissues." (PMID 40315225, 2025).
Klinefelter syndrome (1 paper, 2023). A sex chromosome disorder caused by the presence of an extra X chromosome in the male karyotype. "Moreover, BOD1L2, C1orf194, and KRTCAP2 are found to indicate testicular spermatogenic capacity in a variety of testicular diseases, such as Y‐chromosome microdeletions and Klinefelter syndrome." (PMID 37083227, 2023).
pancreatic cancer (1 paper, 2025). "In our study, pan-cancer analysis had further demonstrated that these 13 hypoxia-related genes, particularly the KRTCAP2 gene, were not only significantly associated with the prognosis of pancreatic cancer but also played critical roles across various malignancies." (PMID 40315225, 2025).
serous ovarian carcinoma (1 paper, 2021). "The chimeric RNAs generated from tripartite motif containing 46 (TRIM46) with MUC1 and KRTCAP2 have been clinically implicated in high-grade serous ovarian carcinoma." (PMID 34722520, 2021).
tumor (5 papers, 2015 to 2026). "Based on these findings, we propose that KRTCAP2 serves as a potential tumor biomarker and represents a promising target for therapeutic intervention." (PMID 40315225, 2025). "Conversely, a positive correlation was observed between KRTCAP2 expression and the immunosuppressive Treg cells, suggesting that KRTCAP2 played a significant role in modulating the tumor immune microenvironment across diverse cancer types." (PMID 40315225, 2025). "Notably, KRTCAP2 expression showed a significant positive association with the density of infiltrating CD68+ and CD163+ tumor-associated macrophages (TAMs)." (PMID 41676149, 2026).
cancer (3 papers, 2015 to 2025). A tumor composed of atypical neoplastic, often pleomorphic cells that invade other tissues. "Additionally, a pan-cancer analysis affirmed the relevance of our hypoxia-related genes across multiple malignancies, particularly highlighting KRTCAP2 as a pivotal biomarker associated with worse prognosis and reduced immune infiltration." (PMID 40315225, 2025). "We further examined KRTCAP2 expression levels in cancer tissues, compared to adjacent normal tissues, and across different stages of cancer progression." (PMID 40315225, 2025). "The results indicated a significant overexpression of KRTCAP2 in cancer tissues across most cancer types, with its abundant expression escalating in higher cancer stages." (PMID 40315225, 2025). "By analyzing the mRNA-seq reads from The Cancer Genome Atlas (TCGA), we uncovered a novel cancer-enriched chimeric RNA as the result of splicing between MUC1, a highly glycosylated transmembrane mucin, TRIM46, a tripartite motif containing protein, and KRTCAP2, a keratinocyte associated protein." (PMID 26492273, 2015).
KRTCAP2 also shares sentences with these, for which no sentence is quoted: ovarian carcinoma (2 papers); dementia (1); infection (1); testicular diseases (1).